POGLUT1 (protein O-glucosyltransferase 1)
Description:
Dual specificity glycosyltransferase that catalyzes the transfer of glucose and xylose from UDP-glucose and UDP-xylose, respectively, to a serine residue found in the consensus sequence of C-X-S-X-P-C. Specifically targets extracellular EGF repeats of protein such as CRB2, F7, F9 and NOTCH2. Acts as a positive regulator of Notch signaling by mediating O-glucosylation of Notch, leading to regulate muscle development. Notch glucosylation does not affect Notch ligand binding. Required during early development to promote gastrulation: acts by mediating O-glucosylation of CRB2, which is required for CRB2 localization to the cell membrane (By similarity).
Synonyms: hCLP46; C3orf9; CLP46; KTELC1; MDSRP; MDS010; MGC32995; 9630046K23Rik; KDELCL1; Rumi; LGMD2Z; LGMDR21
Tractability: Small molecule: a structure with a bound ligand is known. Antibody: UniProt predicts a signal peptide or a membrane-spanning region. PROTAC: ubiquitination databases record sites on it; its protein half-life has been measured.
Gene: Protein-coding gene on chromosome 3 (119,468,963 to 119,494,708, forward strand). Ensembl gene ENSG00000163389.
Subcellular location: Endoplasmic reticulum lumen
Subcellular location (Human Protein Atlas): Endoplasmic reticulum
Pathways (Reactome):
Signal Transduction: Pre-NOTCH Processing in the Endoplasmic Reticulum
Gene Ontology:
Molecular function: EGF-domain serine glucosyltransferase activity; EGF-domain serine xylosyltransferase activity; glucosyltransferase activity; UDP-glucosyltransferase activity; UDP-xylosyltransferase activity
Biological process: muscle tissue development; protein O-linked glycosylation; protein O-linked glycosylation via glucose; protein O-linked glycosylation via xylose; positive regulation of Notch signaling pathway; regulation of gastrulation
Cellular component: endoplasmic reticulum; endoplasmic reticulum lumen; endomembrane system
Genetic constraint (gnomAD): Loss-of-function variants: 17 observed, 30.94 expected, observed/expected ratio (o/e) 0.55, 90% interval 0.38 to 0.82. The upper end of that interval is the gene's LOEUF score, 0.82, which puts it in group 3 of 6, group 1 being the genes least tolerant of losing a copy. Missense variants: 228 observed, 278.99 expected, observed/expected ratio (o/e) 0.82, 90% interval 0.73 to 0.91. Synonymous variants: 102 observed, 95.85 expected, observed/expected ratio (o/e) 1.06, 90% interval 0.91 to 1.25.
Gene-disease validity (ClinGen):
ClinGen rates the evidence that POGLUT1 causes each of these diseases.
autosomal recessive limb-girdle muscular dystrophy (autosomal recessive): Definitive. Autosomal recessive form of limb-girdle muscular dystrophy.
Homologues: Orthologues: chimpanzee POGLUT1 (100% identical), macaque POGLUT1 (99% identical), dog POGLUT1 (95% identical), pig POGLUT1 (94% identical), rabbit POGLUT1 (94% identical), guinea pig POGLUT1 (93% identical), mouse Poglut1 (91% identical), rat Poglut1 (91% identical), zebrafish poglut1 (65% identical), tropical clawed frog poglut1 (61% identical), Drosophila melanogaster rumi (55% identical), Drosophila melanogaster CG31139 (44% identical). Paralogues in human: POGLUT3 (30% identical), POGLUT2 (30% identical).
Diseases named in the same sentence as POGLUT1 in open-access papers:
POGLUT1 is named in the same sentence as 32 diseases in open-access papers, as found by Europe PMC text mining. Sharing a sentence is not in itself a finding about the gene and the disease. The quoted sentences say what the papers report.
limb-girdle muscular dystrophy (6 papers, 2020 to 2025). Limb-girdle muscular dystrophy (LGMD) is a heterogeneous group of muscular dystrophies characterized by proximal weakness affecting the pelvic and shoulder girdles. "Mutations in protein O-glucosyltransferase 1 (POGLUT1) cause a recessive limb-girdle muscular dystrophy (LGMDR21) with reduced satellite cell number and NOTCH1 signaling in adult patient muscles and impaired myogenic capacity of patient-derived muscle progenitors." (PMID 40825068, 2025). "Mutations in protein O-glucosyltransferase 1 (POGLUT1) cause a recessive form of limb-girdle muscular dystrophy (LGMD-R21) associated with reduced satellite cell number and NOTCH1 signaling in adult patient muscles and impaired myogenic capacity of patient-derived muscle progenitors." (PMID 39651163, 2024). "For instance, nine missense mutations and one nonsense recessive variant in POGLUT1 have been described in Limb-girdle muscular dystrophy (LGMD) R21 patients belonging to unrelated families from different countries." (PMID 33670724, 2021). "A study following 4 patients that demonstrate an autosomal recessive limb-girdle muscular dystrophy (LGMD), points to the missense mutation D233E on POGLUT-1 causing Notch signaling reduction, as the primary cause of the disease manifestation." (PMID 35459219, 2022).
muscular dystrophy (6 papers, 2016 to 2025). Muscular dystrophy (MD) refers to a group of more than 30 genetic diseases characterized by progressive weakness and degeneration of the skeletal muscles that control movement. "Currently, three muscle disease genes that interact with the Notch pathway have recently been identified—Jag2, MEGF10, and POGLUT1—whose mutation has been noted in muscular dystrophies." (PMID 36237531, 2022). "Our data link a missense mutation in POGLUT1 to a novel form of muscular dystrophy and suggest that Notch‐dependent loss of satellite cells is the primary pathomechanism for the disease in our patients." (PMID 27807076, 2016). "Our findings demonstrate that D233E mutation in POGLUT1 causes autosomal recessive limb‐girdle muscular dystrophy and implicate a primary defect in muscle progenitor cells as a novel pathomechanism for muscular dystrophy." (PMID 27807076, 2016). "Indeed, this appears to be the case with the family we present carrying a homozygous missense D233E mutation in POGLUT1 gene: a muscular dystrophy as a consequence of defective muscle regeneration." (PMID 27807076, 2016). "We have previously identified a new form of muscular dystrophy called limb-girdle muscular dystrophy autosomal recessive 21 (LGMDR21), which is caused by pathogenic variants in the POGLUT1 (Protein O-Glucosyltransferase 1) gene." (PMID 39651163, 2024).
Dowling-Degos disease (4 papers, 2015 to 2024). A pigmentation disease characterized by a reticulate pattern of abnormally dark skin coloring, particularly in the body's folds and creases. "Whole exome sequencing has demonstrated that human POGLUT1 mutations are responsible for a subset of the cases of Dowling-Degos Disease, an autosomal dominant hyperpigmentation disorder." (PMID 26496195, 2015). "The first human disease associated with POGLUT1 pathogenic variants was Dowling-Degos disease." (PMID 39237981, 2024). "A significant aspect of this review is the exploration of the genetic, histopathological, and clinical parallels between GGD and Dowling-Degos disease (DDD), which is another rare autosomal dominant genodermatosis, particularly focusing on their shared mutations in the KRT5 and POGLUT1 genes." (PMID 38390850, 2024).
acute myeloid leukemia (3 papers, 2014 to 2022). Acute myeloid leukemia (AML) is a group of neoplasms arising from precursor cells committed to the myeloid cell-line differentiation. "According to the previous studies about POGLUT1, a member from the same family of POGLUT2, elevated POGLUT1 expression was found in hematopoietic malignancies, including primary acute myelogenous leukemia and T-ALL." (PMID 36158688, 2022). "Protein O-glucosyltransferase 1 (POGLUT1) is a novel gene that was initially isolated and identified from the bone marrow cells of patients with myelodysplastic syndrome/acute myeloid leukemia." (PMID 25009645, 2014).
breast carcinoma (3 papers, 2014 to 2021). "POGLUT1 is overexpressed in several human leukemia, breast cancer and endometrial cancer cell lines." (PMID 26496195, 2015). "In the present study, pBabe-POGLUT1-myc(pBaPM) retrovirus was recombined, which overexpresses exogenous POGLUT1 in human breast cancer BT474 cells." (PMID 25009645, 2014). "The present study found that the signaling pathway of POGLUT1 in BT474 human breast cancer cells involves a POGLUT1/Smad3/p16/CDK/pRb pathway, and the signal is increased by TGF-β1." (PMID 25009645, 2014). "Previous studies have reported that BT474 human breast cancer cell growth increases in response to POGLUT1 overexpression due to POGLUT1-induced inhibition of transforming growth factor β1 (TGF-β1)-mediated induction of INK4a gene expression." (PMID 25009645, 2014). "In the present study, in order to investigate the function and target of POGLUT1 in BT474 breast cancer cells, the effect of POGLUT1 on cell proliferation, differentiation, apoptosis and key proteins in the transforming growth factor (TGF)-β1 signaling pathway was investigated in BT474 cells." (PMID 25009645, 2014). "Thus, investigations into the mechanism, interacting molecules and regulation of POGLUT1 in tumor cells are required, particularly in breast cancer which affects numerous females worldwide." (PMID 25009645, 2014). "First, the recombinant retrovirus vector pBabe-puro-POGLUT1-Myc was constructed in vitro, then transformed and packaged into an integral virus, which was used to transfer the POGLUT1 gene into BT474 human breast cancer cells in order to investigate the function and mechanism of POGLUT1." (PMID 25009645, 2014).
colorectal cancer (2 papers, 2021 to 2025). A primary or metastatic malignant neoplasm that affects the colon or rectum. "POGLUT1 expression has been observed to be significantly elevated in colorectal cancer tissues compared to adjacent noncancerous areas, with overexpression linked to advanced TNM stages, lymph node metastasis, and shorter survival times." (PMID 39886381, 2025). "Similarly, downregulated POGLUT1 in colorectal cancer (CRC) cells that showed significantly higher expression of POGLUT1 than noncancerous cells prevented illegitimate CRC cell proliferation." (PMID 33436558, 2021).
primary biliary cholangitis (2 papers, 2019 to 2021). Primary biliary cholangitis (PBC) is a chronic and slowly progressive cholestatic liver disease of autoimmune etiology characterized by injury of the intrahepatic bile ducts that may eventually lead to liver failure. "Also, POGLUT1 mutation has been reported in primary biliary cholangitis (PBC), a chronic and progressive autoimmune liver disease induced by disruption of small bile ducts." (PMID 33436558, 2021).
breast ductal adenocarcinoma (1 paper, 2014). A breast carcinoma arising from the ducts. "In order to investigate the role of POGLUT1 in tumor cell proliferation, a recombinant, Myc-labeled retroviral vector, babe-puro-POGLUT1-Myc, was constructed and transduced into BT474 human breast ductal adenocarcinoma cells to induce exogenous POGLUT1 overexpression." (PMID 25009645, 2014).
cervical cancer (1 paper, 2022). A primary or metastatic malignant neoplasm involving the cervix. "Compared with normal cervix tissues, the expressions of several glycosyltransferases in cervical cancer tissues were upregulated, including GALNT2, POGLUT1, EXT1, B3GAT3, B4GALNT1 and UGT8 (GSE9750)." (PMID 36110252, 2022).
congenital nephrosis (1 paper, 2015). "Mutations in human CRUMBS2 are associated with some cases of congenital nephrosis, suggesting that POGLUT1 is also a candidate gene in this human syndrome." (PMID 26496195, 2015).
Hepatitis B (1 paper, 2024). "According to our study, the reactome pre-Notch expression including POGLUT1 and HIST1H2BC was associated with a risk of Hepatitis B in Taiwanese men when compared to women." (PMID 39237981, 2024). "In conclusion, this study is the first to identify that POGLUT1 and HIST1H2BC only appeared in males, not in females, and were associated with the risk of Hepatitis B in Taiwanese individuals." (PMID 39237981, 2024). "We found that two specific genes, called POGLUT1 and HIST1H2BC, were only linked to hepatitis B risk in men, not in women." (PMID 39237981, 2024).
Leber congenital amaurosis (1 paper, 2015). Leber congenital amaurosis (LCA) is a retinal dystrophy defined by blindness and responses to electrophysiological stimulation (Ganzfeld electroretinogram (ERG)) below threshold, associated with severe visual impairment within the first year of life. "Mutations in EGF repeats of human CRUMBS1, another likely substrate of POGLUT1, are found in retinitis pigmentosa and Leber congenital amaurosis, and could affect the glycosylation status of CRUMBS1 and its membrane localization in the eye." (PMID 26496195, 2015).
liver disease (1 paper, 2020). "This suggested that humans with a known JAG1 mutation and overexpression of POGLUT1 (the human homolog for Rumi) may have worse liver disease." (PMID 33172025, 2020).
lymphoma (1 paper, 2014). A malignant (clonal) proliferation of B- lymphocytes or T- lymphocytes which involves the lymph nodes, bone marrow and/or extranodal sites. "It has been demonstrated that POGLUT1 stimulates the proliferation of U937 human lymphoma cells and inhibits the TGF-β-induced inhibition of U937 cell growth, suggesting that POGLUT1 may be a cytokine which promotes and sustains tumor cell malignant transformation." (PMID 25009645, 2014).
monocytic leukemia (1 paper, 2021). "Subsequently, a higher growth rate of POGLUT1 overexpressed U937 cells (monocytic leukemia cell line) in comparison to cells without exogenous POGLUT1 had confirmed the association of POGLUT1 with AML progression, which might occur by inhibiting the CDKIs through Notch signaling." (PMID 33436558, 2021).
multiple sclerosis (1 paper, 2019). A progressive autoimmune disorder affecting the central nervous system resulting in demyelination. "Regardless, rs2293370, whose effector gene is POGLUT1, may operate as a functional SNP in both PBC and multiple sclerosis." (PMID 30643196, 2019).
cancer (2 papers, 2014 to 2022). A tumor composed of atypical neoplastic, often pleomorphic cells that invade other tissues. "Increased expression of POFUT1 and POGLUT1 has been found in several cancers, including brain tumors, hepatocellular carcinoma, colorectal cancer, and oral squamous cell carcinoma." (PMID 35335147, 2022). "However, further investigations on how POGLUT1 interacts with these proteins and how POGLUT1 affects Smad3 phosphorylation levels are required in order to understand the specific mechanism of POGLUT1 in cancer." (PMID 25009645, 2014). "Notably, different types of cancers exhibit aberrant expression of Notch-modifying glycosyltransferase genes, such as POFUT1, POGLUT1, or Fng." (PMID 35335147, 2022).
tumor (2 papers, 2014 to 2015). "POGLUT1 may have an important role in cellular self-renewal and the development of various normal and malignant tumor cells." (PMID 25009645, 2014). "POGLUT1 overexpression was observed to decrease the phosphorylation of Smad3 and the expression of p16 was found to decrease to a level even lower than the background level, as the normal negative feedback regulation mechanism is already impaired in tumor cells." (PMID 25009645, 2014).
dermatosis (1 paper, 2016). "Therefore, since patients homozygous for D233E have deficient enzymatic activity but normal POGLUT1 expression and no skin abnormalities, this dermatosis could be due to a defect in a non‐enzymatic function of POGLUT1." (PMID 27807076, 2016).
POGLUT1 also shares sentences with these, for which no sentence is quoted: autosomal recessive limb-girdle muscular dystrophy (2 papers); endometrial cancer (2); autosomal dominant disease (1); Dent Disease 2 (1); Keratitis-Ichthyosis-Deafness syndrome (1); leukemia (1); lymph node metastasis (1); muscle disorders (1); myelodysplastic syndrome (1); oral squamous cell carcinoma (1); pachyonychia congenita (1); retinal degeneration (1); retinitis pigmentosa (1).